SRGN (serglycin)
Diseases named in the same sentence as SRGN in open-access papers (continued):
Sharing a sentence is not in itself a finding about the gene and the disease.
infection (11 papers, 2009 to 2025). The state of being infected such as from the introduction of a foreign agent such as serum, vaccine, antigenic substance or organism. "Here the serglycin-deficient (SG−/−) mouse strain was used to investigate the impact of SG on intestinal immune responses during infection with the non-invasive protozoan parasite Giardia intestinalis." (PMID 34335577, 2021). "At five weeks post infection, increased larvae burden and inflammation were seen in the muscle tissue of the serglycin-deficient mice." (PMID 27267469, 2016). "Proteins downregulated by infection included serglycin (XP_021436653.1), poliovirus receptor-like (XP_021427658.1), LOC110509104 (XP_021445743.1), and apolipoprotein B-100-like (XP_021467197.1 and XP_021467201.1)." (PMID 37928534, 2023). "Here we investigated the potential role of serglycin proteoglycans in host defense after infection with the nematode Trichinella spiralis." (PMID 27267469, 2016). "Our results suggest that during infection with T. spiralis, serglycin proteoglycans play a pivotal role in both early and late host immune responses." (PMID 27267469, 2016). "Seeing the prominent effects at 12 dpi in the SG−/− mice, we finally evaluated if serglycin proteoglycans also play a role 5 weeks post infection in the chronic phase of T. spiralis infection." (PMID 27267469, 2016). "Super-infection of the BL cell line Raji resulted in an increase of serglycin on the cell surface suggesting an involvement of EBV-infection in transcriptional regulation of serglycin." (PMID 26527314, 2015). "The present data thus support a prominent role for serglycin proteoglycan in host defense and also introduce the possibility to utilize serglycin as a biomarker for infection." (PMID 19956711, 2009). "Since MCs and serglycin proteoglycans may contribute to the pro-inflammatory cytokine signaling during infection, we analyzed the serum levels of the pro-inflammatory cytokines TNF-α and IL-1β, and the regulatory cytokine IL-10." (PMID 27267469, 2016). "This suggests that lack of serglycin proteoglycans continues to cause problems for the mice at 5 weeks post infection." (PMID 27267469, 2016). "Nevertheless, deletion of the serglycin, the core protein that organizes the MC granule proteoglycan scaffold, resulted in highly elevated S.Tm colonization of both vacuolar and cytosolic compartments, as well as an elevated frequency of MC death following infection." (PMID 40838737, 2025). "However, little is known about the in vivo functions of serglycin proteoglycans during infection." (PMID 27267469, 2016). "The higher expression of FTH1, ISG15, SRGN and S100A12 genes observed in infected animals suggests the activation of the host immune system to resist the infection." (PMID 37761803, 2023). "Given the heparan sulfate-dependent enhanced attachment and infection of SARS-CoV-2 virus, it will be interesting to evaluate a model where serglycin as a critical mediator between SARS-CoV-2 infection, mast cell activation and the pulmonary pathology." (PMID 33435561, 2021). "Among them, 25 genes, such as arachidonate 15-lipoxygenase (ALOX15), collagen, type VI, α5 (COL6A5), and serglycin (SRGN), were significantly upregulated while the expression of transthyretin (TTC) was repressed by infection." (PMID 27197554, 2016). "Interestingly, the reconstitution with serglycin-competent bone marrow derived MCs restored the IL-13 levels almost to WT levels, suggesting that serglycin-competent MCs may contribute an important part of the IL-13 secreted during infection." (PMID 27267469, 2016). "Previously we have shown that the deletion of serglycin affected the levels of NE in naïve mice, whereas MPO levels were unaffected, and that early neutrophil recruitment was delayed in the SG−/− mice during infection with T. gondii." (PMID 27267469, 2016).
adenocarcinoma (2 papers, 2015 to 2017). A common cancer characterized by the presence of malignant glandular cells. "Four top performing EV-associated proteins that distinguished adenocarcinoma cases from controls, SRGN, TPM3, THBS1 and HUWE1, yielded a combined area under the receiver operating characteristic curve (AUC) of 0.90 (95% CI = 0.76-1)." (PMID 29221141, 2017). "On the contrary, there was no high-grade adenocarcinoma exhibiting low-grade (1+) serglycin immunoreactivity in the samples tested." (PMID 26581653, 2015).
blood disorders (2 papers, 2015 to 2019). "Although numerous studies have shown that serglycin is involved in hematological malignancies, not much information has been published on the expression and distribution of this proteoglycan in solid tumors." (PMID 26581653, 2015). "Surprisingly, one of the higher abundant proteins, serglycin (SRGN) was previously reported as a marker of AML, not upregulated in PV, and therefore allowing distinction between those two blood disorders." (PMID 31064135, 2019).
SRGN also shares sentences with these, for which no sentence is quoted: lymphoma (2 papers); Sepsis (2); acute monocytic leukemia (1); Alzheimer disease (1); anaplastic gliomas (1); astrocytomas (1); B-cell lymphoma (1); bladder urothelial carcinoma (1); Breast invasive carcinoma (1); cardiovascular disease (1); chondrosarcoma (1); colon adenocarcinoma (1); endometrial carcinoma (1); Ewing sarcoma (1); experimental autoimmune encephalomyelitis (1); follicular dendritic cell sarcoma (1); giant cell tumor (1); Gliosis (1); head and neck cancer (1); heart failure (1); intestinal cancer (1); kidney cancer (1); kidney chromophobe (1); Lung squamous cell carcinoma (1); medulloblastoma (1); mesothelioma (1); metabolic syndrome (1); neuroblastoma (1); neurological diseases (1); oligoastrocytoma (1).
A further 12 diseases each share a sentence with SRGN in 1 paper.